NR4A1 (nuclear receptor subfamily 4 group A member 1)
Diseases named in the same sentence as NR4A1 in open-access papers (continued):
Sharing a sentence is not in itself a finding about the gene and the disease.
melanoma (continued). "Nr4a1 co-localizes with Bcl-2 in the mitochondria in prostate cancer cells, melanoma cells and gastric cancer cells These data confirm that Nr4a1 has extra-nuclear functions, independent of DNA binding, as part of the intrinsic apoptotic pathway to induce cytochrome c release." (PMID 31683815, 2019). "NR-V04 was found to efficiently degrade NR4A1 within the TME and elicit anti-tumor effects consistent with the upregulation of tumor-infiltrating B cells in mouse melanoma models." (PMID 40508074, 2025). "Following 16 h treatment, NR-V04 induced a dose-dependent decrease of NR4A1 protein in CHL-1 cells with a 50% degradation concentration (DC50) of 228.5 nM and in A375 melanoma cells with DC50 of 518.8 nM." (PMID 38334978, 2024). "The study introduces a new immunotherapy for treating melanoma and other cancers by developing a PROTAC that degrades NR4A1, an intracellular nuclear factor that plays a crucial role in immune suppression." (PMID 38334978, 2024). "NR-V04 treatment also reduced NR4A1 protein level in WM164 and M229 human melanoma cells and SM1 and SW1—two mouse melanoma cell lines." (PMID 38334978, 2024). "In melanoma, NR4A1 is expressed across multiple cell types within the TME, and most TI immune cells showed elevated NR4A1 expression relative to their blood counterparts." (PMID 38334978, 2024). "In the melanoma tumor microenvironment, T-cell receptor (TCR) signaling can trigger its downstream NR4A1 expression, so using NR4A1-GFP indicated that blocking β-AR signaling increased metabolic reprogramming of CD8+ T-cell activation via TCR signaling." (PMID 36052242, 2022). "The overexpressed NR4A1 can bind to and activate the rate-limiting enzyme trifunctional protein β (TPβ) to maintain ATP and NADPH levels and prevent ROS increase and melanoma cell death." (PMID 36052242, 2022). "We further analyzed NR4A1 expression within several single-cell RNA sequencing datasets, including human hepatocellular carcinomas (HCC; GEO: GSE98638) and melanomas (GEO: GSE148190, GSE158803)." (PMID 38334978, 2024). "We recently synthesized a panel of celastrol-based NR4A1 PROTAC degraders, some of which have outstanding efficiency in the degradation of NR4A1 in cancer cell lines as well as in syngeneic tumor models including B16 melanoma and MC38 colon cancer models." (PMID 39872303, 2023). "In human disease, NR4A1 is highly expressed in the vasculature and tumor cells of human melanoma and CRC tissues, but not in normal tissues." (PMID 33634114, 2021). "To determine whether NR4A1 plays important roles in the TME, we implanted three syngeneic tumors into wild-type (WT) or NR4A1−/− (KO) mice, including the MC38 colon cancer model, and Yummer1.7 and B16F10, the two melanoma models." (PMID 38334978, 2024). "Leveraging The Cancer Genome Atlas (TCGA) datasets, we investigated NR4A1 expression in melanoma patients and identified a negative correlation between NR4A1 and genes involved in the antitumor immune responses, including IFNγ (interferon γ), GZMB (granzyme B), and PRF1 (perforin)." (PMID 38334978, 2024). "To validate NR4A1 as the primary molecular target of NR-V04 in the TME, we inoculated B16F10 melanoma tumors in NR4A1−/− mice and found that NR-V04 failed to inhibit B16F10 in these mice." (PMID 38334978, 2024). "We highlight how NR4A1 in immune cells within the TME may be either a positive (e.g., macrophages in colon cancer) or negative prognostic factor (e.g., T cells in melanoma), depending on the cancer and immune cell context." (PMID 40508074, 2025).
lung cancer (43 papers, 2010 to 2026). A malignant neoplasm involving the lung. "In lung cancer models, NR4A1-deficient mice had increased NK cells within the TME and decreased metastasis." (PMID 40508074, 2025). "NR4A1 encodes for the orphan nuclear receptor A1 for which a strong association with unfavorable outcome in lung cancer has been shown and is involved in cancer cell migration." (PMID 33960931, 2021). "On the contrary, it is reported that NR4A1 is overexpressed in bladder, breast, pancreatic, colon, and lung cancer and is associated with poor survival in breast and lung cancer patients." (PMID 33172112, 2020). "An association between clinical outcomes of lung cancer patients and NR4A1 expression was examined using the Kaplan–Meier plot." (PMID 33172112, 2020). "The immune responses involving Nr4a1 suppression might relate to complete remission of lung cancer in this case, despite causing SJS, which may be attributed to synergistic effects from pembrolizumab treatment and intervention with steroids." (PMID 36464708, 2022). "Although the role of NR4A1 in lung cancer remains to be verified, a growing number of studies have found that NR4A1 plays a pro-cancer role in lung cancer." (PMID 40666103, 2025). "The aim of this article is to summarize the regulatory role and mechanism of NR4A1 in lung cancer to provide a sound theoretical basis for the clinical treatment of lung cancer." (PMID 40666103, 2025). "NR4A1 is regulated at both the transcriptional and post-transcriptional levels and regulates downstream signaling pathways involved in lung cancer processes, including angiogenesis, cell proliferation, migration, invasion, apoptosis, and immune regulation." (PMID 40666103, 2025). "This review summarizes the biological role of NR4A1 in lung cancer and describes the molecular mechanisms and signaling pathways regulated by NR4A1." (PMID 40666103, 2025). "collected RNA-seq data from 1013 lung cancer cases and 397 normal tissue samples from the TCGA and GTEx databases and found that NR4A1 expression was lower in lung adenocarcinoma (LUAD) and lung squamous cell carcinoma (LUSC) than in normal tissue." (PMID 40666103, 2025). "NR4A1 plays a pro-cancer role in solid tumors including lung cancer, but a tumor suppressor role in hematological malignancies." (PMID 40666103, 2025). "In recent years, studies have shown that targeted inhibition of NR4A1 can play an important role in preventing the development of lung cancer." (PMID 40666103, 2025). "According to our current understanding, NR4A1 plays an important role in the occurrence and development of lung cancer." (PMID 40666103, 2025). "Recent studies have found that nuclear receptor NR4A1 is widely expressed in a variety of tumors, including lung cancer." (PMID 40666103, 2025). "In recent years, several studies on NR4A1-related agonists and inhibitors in lung cancer have been reported." (PMID 40666103, 2025). "The role of NR4A1 in lung cancer involves multiple aspects, including transcriptional regulation, protein-protein interactions, and post-translational modifications." (PMID 40666103, 2025). "Stimulation by serum and epidermal growth factor induces trans-activation of NR4A1 in H460 and Calu-6 lung cancer cells, and high expression of NR4A1 promotes cell cycle progression, exerting a positive effect on mitosis in lung cancer cells." (PMID 40666103, 2025). "Beyond CD8+ T cells, in colon cancer and lung carcinoma models, NR4A1 inhibition has been shown to decrease the suppressive function of Tregs through the reduced expression of CD25 and cytotoxic T-lymphocyte-associated antigen 4 (CTLA4)." (PMID 40508074, 2025).
lung cancer (continued). "Nr4a1 was also shown to facilitate TGF-β-induced lung cancer cells invasion and embryonal rhabdomyosarcoma cells invasion." (PMID 37161357, 2023). "We describe a case of Stevens-Johnson syndrome (SJS) that was induced by a single dose of pembrolizumab and successfully treated with steroids, leading to complete remission of lung cancer during the monitoring of immune response indices, including Nr4a1 mRNA." (PMID 36464708, 2022). "This revealed that the level of NR4A1 mRNA was correlated inversely with the overall survival of patients with adenocarcinoma or any type of lung cancer." (PMID 33172112, 2020). "Phosphorylation of Nr4a1 at Ser351 by Akt blocks mitochondrial targeting in H460 lung cancer cells and BGC-823 gastric cancer cells." (PMID 31683815, 2019). "In lung cancer patients, high expression of NR4A1 was a prognostic indicator for decreased survival." (PMID 29498706, 2018). "NR4A1 is retained in the nucleus through its interaction with T-cell lymphoma invasion and metastasis-inducing protein 1, preventing Bcl-2 activation and contributing to lung cancer cell survival." (PMID 40746844, 2025). "Additionally, NR4A1 plays a critical role in the TGFβ-induced invasion of breast and lung cancer cells." (PMID 40361912, 2025). "However, there is still a long way to go in researching NR4A1 as a target for chemoprevention of lung cancer." (PMID 40666103, 2025). "Lee’s group found that NR4A1 promotes the proliferation of lung cancer cells in two ways." (PMID 40666103, 2025). "Research progress of NR4A1 inhibitors and agonists in lung cancer." (PMID 40666103, 2025). "Research progress of other compounds of NR4A1 in lung cancer." (PMID 40666103, 2025). "In the immune system, NR4A1 regulates the immune response mainly by inhibiting the recognition and proliferation of T cells, thus reducing the body’s ability to monitor and attack lung cancer cell." (PMID 40666103, 2025). "In addition, NR4A1 exerts an important part in the regulation of TGFβ-induced invasion and migration of lung cancer cells." (PMID 33014809, 2020). "On the other hand, NR4A1 is commonly overexpressed in lung cancer patients and correlates to poor prognosis, and it has been shown to confer a proliferative advantage to colon cancer cells as well as increasing the invasive behavior of breast cancer by enhancing TGFβ signaling." (PMID 25269081, 2014). "However, in other studies, e.g. using endothelial cells and lung cancer cells, NR4A1 promotes cell proliferation." (PMID 25269081, 2014). "In future clinical applications, in addition to the use of cisplatin, Nimotuzumab, and Bevacizumab alone in the treatment of lung cancer, the combination of NR4A1-targeted drugs with monoclonal antibody chemotherapy may provide a better treatment option for patients." (PMID 40666103, 2025). "used the STRING database to show that NR4A1 expression correlates with RNA polymerase I subunit B (POLR1B) activity, and POLR1B is an important modulator of lung cancer cell proliferation." (PMID 40666103, 2025). "Akt phosphorylates NR4A1 at serine 351 and promotes NR4A1 translocation from the nucleus to the cytoplasm in 293, NIH 3T3, H460 lung cancer cells." (PMID 40746844, 2025). "collected tissue from 59 patients with NSCLC and adjacent normal lung tissue and, by immunohistochemical analysis, showed that NR4A1 was expressed in lung cancer but there was low or no expression in normal lung tissue." (PMID 40666103, 2025). "NR4A1 promotes the expression of inhibitory receptors, such as programmed cell death-1 (PD-1), leading to the depletion or dysfunction of CAR T cells, which ultimately allows lung cancer cells to evade the immune response." (PMID 40666103, 2025).
lung cancer (continued). "Results of analysis of gene expression data from female non-smoking lung cancer patients identified NR4A1 as a potential target gene and they demonstrated that nilotinib, a protein-tyrosine kinase inhibitor, was also an NR4A1 ligand that inhibited lung cancer cell growth." (PMID 38116863, 2024). "However, another report showed that TGF-β-induced nuclear export of NR4A1 in lung cancer cells is JNK-dependent and not p38 dependent." (PMID 33995055, 2021).
ovarian carcinoma (43 papers, 2003 to 2026). A malignant neoplasm originating from the surface ovarian epithelium. "Thus, the expression patterns of NR4A1 appear to differ between endometriosis and endometrial or ovarian cancers, suggesting different regulatory mechanisms." (PMID 39408909, 2024). "Moreover, recent studies have shown that NR4A1 induces TNFα-mediated apoptosis sensitivity in human gastric cancer and improves cisplatin resistance in ovarian cancer, supporting that NR4A1 plays a crucial role in drug therapy sensitivity in a variety of tumor models." (PMID 34209871, 2021).
diabetes (40 papers, 2013 to 2026). "Expression analysis of diabetes-associated DEGs such as CXCL8, IL7R, and NR4A1 showed significant alterations after 20(R)-Rg3 treatment." (PMID 41373625, 2025). "This is associated with a reduction of Lcn10 expression in macrophages, resulting in: 1) an exacerbated inflammation through disrupting Nr4a1 signal, 2) a high ratio of pro-/anti-inflammatory macrophage population accumulated in the heart during diabetes." (PMID 35757735, 2022). "Seeking ways or drugs to enhance NR4A1 expression in our body would be helpful to reduce the possibility of diabetes development." (PMID 34088892, 2021). "Nuclear orphan receptor subfamily 4 group A member 1 (NR4A1), an important regulator of hepatic glucose homeostasis, was found to interact with the nuclear glycerol kinase Gyk during hepatic gluconeogenesis in the unfed state and in diabetes." (PMID 40717128, 2025). "NR4A1 functioned as an intrinsic inhibitor of diabetes-induced myocardial fibrosis." (PMID 39114353, 2024). "Our study indicates NR4A1 might be a major player in the protective network of pancreatic β‐cells, and our finding might provide clues for β‐cell protection and diabetes prevention." (PMID 33124187, 2020). "Supporting evidence includes an increased susceptibility in NR4A1 deficient mice for experimental autoimmune encephalomyelitis (EAE; 2D2 transgenic TCR model), allergic contact dermatitis, collagen-induced arthritis, and diabetes." (PMID 33597928, 2020). "Single deficiency in either NR4A1 or Bim did not result in broken tolerance, however, combined deficiency resulted in broken self-tolerance signified by the development of diabetes." (PMID 33597928, 2020). "However, understanding the specific role of NR4A1 in the regulation of inflammation in diabetes requires further study." (PMID 25289075, 2014). "Moreover, we determined that AMPK signaling-mediated nuclear receptor subfamily 4 group A member 1 (NR4A1) suppression might induce mitochondrial homeostasis to protect cardiomyocytes against diabetes-induced mitochondrial dysfunction and oxidative stress." (PMID 35360240, 2022). "NR4A1 can reduce endoplasmic reticulum stress or ROS by enhancing MKP7 expression to reduce pancreatic beta cell apoptosis, which can effectively prevent diabetes." (PMID 37131205, 2023). "Treatment of BDC mice with αCD3 Ab (clone 2C11), a therapy shown to reverse diabetes in NOD mice, however, decreased expression of Foxo1-axis genes but increased expression of TCR-driven genes (Irf4, Nr4a1, Cd25, Cd69, Tbx21) in PLN BDC CD4+ T cells." (PMID 34314385, 2021). "The results of this study enrich the knowledge of NR4A1 downregulating JNK over-activation and provide clues for β cell protection or even diabetes prevention." (PMID 34088892, 2021). "NR4A1 recruits TGF-β target genes, SIN3A, and histone deacetylase 1 (HDAC1) to form a repressor complex, countering the TGF-β-mediated pro-fibrotic effects in diabetes." (PMID 39114353, 2024). "In addition, NR4A1 expression was shown to significantly correlate with the levels of the inflammatory cytokines, TNF-α and IL-6, as well as the diabetes-related parameters, FIN, FBG, HOMA-IR and FFA." (PMID 25289075, 2014). "Furthermore, they concluded that microsomal PTGES-2 promotes aging of β-cells and their hypofunction via the PGE/EP3/NR4A1 axis, and drug blocking of microsomal PTGES-2 might have a therapeutic effect on aging-induced beta cellular hypofunction and diabetes." (PMID 37867507, 2023).
colon carcinoma (37 papers, 2010 to 2025). "The results demonstrate that NR4A1 plays an important intratumoral pro-oncogenic role in colon cancer and other solid tumors and is also linked to T-cell exhaustion." (PMID 37847301, 2023). "A comparison of the effects of NR4A1 and NR4A2 knockdown and the DIM-3,5 dual NR4A1/NR4A2 ligands on colon cancer cell migration and apoptosis (TUNEL assay) was also investigated in SW480 cells." (PMID 40332813, 2025). "Immunohistochemical staining of 20 colon tumors and 20 normal colon tissues showed that the proportion of colon tumors with high NR4A1 staining was as high as 60% (12/20), while that of normal colon tissues was only 10% (2/20)." (PMID 40666103, 2025). "Studies in our laboratory have focused on developing agents that target the orphan nuclear receptor 4A1 (NR4A1, Nur77) in solid tumors including colon cancer cells." (PMID 40332813, 2025). "In summary, results of this study show that NR4A1 antagonists inhibit colon tumor growth and decrease NR4A1-regulated expression of the checkpoint inhibitor PD-L1." (PMID 37847301, 2023). "PD-L1 and NR4A1 are also co-expressed in colon cancer cells and treatment with CDIM/NR4A1 antagonists also decreased PD-L1 levels in colon cancer cells." (PMID 37847301, 2023). "An immune competent syngeneic mouse model using mouse MC-38 colon cancer cells which express both NR4A1 and PD-L1 was used." (PMID 37847301, 2023). "The results of studies in RKO, SW480 and MC-38 colon cancer cells show that knockdown of NR4A1 or treatment with DIM-3,5-Cl2 and DIM-3-Br-5-OCF3 decreases PD-L1 expression." (PMID 37847301, 2023). "NR4A1 antagonists inhibited colon tumor growth and downregulated expression of PD-L1 in mouse colon MC-38-derived tumors and cells." (PMID 37847301, 2023). "The results show that piperlongumine decreased luciferase activity in RKO, SW480, and HCT116 colon cancer cells demonstrating the NR4A1 inverse agonist activity of piperlongumine for this transactivation response." (PMID 37808182, 2023). "This study investigated the effects of potent bis-indole-derived NR4A1 antagonists on reversing T-cell exhaustion and downregulating PD-L1 in colon tumors/cells." (PMID 37847301, 2023). "In summary results of this study show that piperlongumine binds the orphan nuclear receptor NR4A1 and acts as an inverse receptor agonist in colon cancer cells." (PMID 37808182, 2023). "NR4A1 transcriptionally inhibits the expression of Dicer to activate downstream Akt/mTORC1 signaling, thereby inducing colon cancer epithelial-to-mesenchymal transition (EMT)." (PMID 36052242, 2022). "Studies have shown that the overexpressed NR4A1 can activate the Wnt/β-catenin signaling pathway to enhance colon tumor growth, colony formation, and migration." (PMID 36052242, 2022). "NR4A1 has been found overexpressed in lung, pancreatic, and colon carcinoma, exhibiting a tumor-promoting effect." (PMID 32664456, 2020). "NR4A1 exhibits pro-oncogenic activity in cancer cell lines derived from solid tumors and was overexpressed in tumors from lung, pancreatic, and colon cancer patients." (PMID 29498706, 2018). "Both IDH1 and TXNDC5 are regulated by NR4A1 in pancreatic and colon cancer cells, and knockdown of either NR4A1 or TXNDC5 in pancreatic cancer cells results in the induction of ROS." (PMID 27144436, 2016). "NR4A1 is overexpressed in lung, breast, pancreatic and colon cancer patients, and functional studies show that NR4A1 is pro-oncogenic and plays a role in cancer cell proliferation, survival, migration and invasion [reviewed in 9]." (PMID 27144436, 2016).